GPR141 (G protein-coupled receptor 141)
Description:
Orphan receptor.
Synonyms: PGR13
Tractability: Small molecule: it belongs to a druggable protein family. Antibody: UniProt places it where antibodies can reach, with medium confidence; UniProt predicts a signal peptide or a membrane-spanning region; its Gene Ontology location is reachable by antibodies, with medium confidence.
Target class: Family A G protein-coupled receptor; Membrane receptor
Gene: Protein-coding gene on chromosome 7 (37,683,721 to 37,833,788, forward strand). Ensembl gene ENSG00000187037.
Subcellular location: Cell membrane
Gene Ontology:
Molecular function: protein binding; G protein-coupled receptor activity; oxysterol binding
Biological process: G protein-coupled receptor signaling pathway
Cellular component: plasma membrane; membrane
Genetic constraint (gnomAD): Loss-of-function variants: 6 observed, 7.79 expected, observed/expected ratio (o/e) 0.77, 90% interval 0.42 to 1.5. That is too few expected variants to judge how well the gene tolerates losing a copy. Missense variants: 372 observed, 392.6 expected, observed/expected ratio (o/e) 0.95, 90% interval 0.87 to 1.03. Synonymous variants: 140 observed, 150.77 expected, observed/expected ratio (o/e) 0.93, 90% interval 0.81 to 1.07.
Homologues: Orthologues: chimpanzee GPR141 (99% identical), macaque GPR141 (94% identical), dog GPR141 (83% identical), rabbit GPR141 (82% identical), mouse Gpr141 (81% identical), pig GPR141 (80% identical), rat Gpr141 (80% identical), guinea pig GPR141 (78% identical), tropical clawed frog gpr141 (43% identical), zebrafish gpr141 (36% identical). Paralogues in human: RXFP3 (20% identical), GPR183 (18% identical), GPR132 (17% identical), GPR174 (16% identical), GPR151 (14% identical), P2RY11 (14% identical), GPR146 (10% identical).